MRPL54 (mitochondrial ribosomal protein L54)
Synonyms: L54mt; MRP-L54; mL54
Tractability: Small molecule: a structure with a bound ligand is known. PROTAC: its protein half-life has been measured.
Gene: Protein-coding gene on chromosome 19 (3,762,672 to 3,768,575, forward strand). Ensembl gene ENSG00000183617.
Subcellular location: Mitochondrion
Subcellular location (Human Protein Atlas): Mitochondria
Pathways (Reactome):
Metabolism of proteins: Mitochondrial ribosome-associated quality control; Mitochondrial translation elongation; Mitochondrial translation initiation; Mitochondrial translation termination
Gene Ontology:
Molecular function: protein binding; RNA binding; structural constituent of ribosome
Biological process: mitochondrial translation
Cellular component: mitochondrial large ribosomal subunit; mitochondrion; mitochondrial inner membrane
Genetic constraint (gnomAD): Loss-of-function variants: 12 observed, 16.55 expected, observed/expected ratio (o/e) 0.73, 90% interval 0.46 to 1.17. The upper end of that interval is the gene's LOEUF score, 1.17, which puts it in group 5 of 6, group 1 being the genes least tolerant of losing a copy. Missense variants: 178 observed, 195.83 expected, observed/expected ratio (o/e) 0.91, 90% interval 0.8 to 1.03. Synonymous variants: 91 observed, 80.16 expected, observed/expected ratio (o/e) 1.14, 90% interval 0.96 to 1.35.
Homologues: Orthologues: chimpanzee MRPL54 (99% identical), macaque MRPL54 (88% identical), dog MRPL54 (78% identical), guinea pig MRPL54 (78% identical), pig MRPL54 (76% identical), rat Mrpl54 (69% identical), mouse Mrpl54 (68% identical), tropical clawed frog mrpl54 (50% identical), zebrafish mrpl54 (48% identical), Drosophila melanogaster mRpL54 (38% identical), Caenorhabditis elegans mrpl-54 (31% identical).
Diseases named in the same sentence as MRPL54 in open-access papers:
MRPL54 is named in the same sentence as 12 diseases in open-access papers, as found by Europe PMC text mining. Sharing a sentence is not in itself a finding about the gene and the disease. The quoted sentences say what the papers report.
breast carcinoma (4 papers, 2020 to 2024). "In a recent study on the prediction and classification of breast cancer proteins, MRPL54 is one of the RNA-binding proteins associated with breast cancer." (PMID 33238645, 2020). "used the machine-learning classification model to recognize that MRPL54 may be strongly connected to breast cancer." (PMID 33251144, 2020).
hepatocellular carcinoma (2 papers, 2022 to 2024). A malignant tumor that arises from hepatocytes. "MRPL54 was used in two separate survival risk prediction gene signatures in hepatocellular carcinoma patients." (PMID 39354291, 2024). "MRPL54 expression has been used to predict outcomes in hepatocellular carcinoma and basal breast cancer." (PMID 39354291, 2024). "MRPL54, EZH2, PPARGC1A, and EIF2AK4 were identified as hub genes in bioinformatics analysis of hepatocellular carcinoma (HCC)." (PMID 35719986, 2022).
adenoma (1 paper, 2026). A neoplasm arising from the epithelium. "We show that Mrpl54 heterozygosity does not alter adenoma formation, intestinal proliferation or apoptosis in a heterozygous Apc model." (PMID 41801951, 2026).
colorectal cancer (1 paper, 2026). A primary or metastatic malignant neoplasm that affects the colon or rectum. "Furthermore, diminished Mrpl54 expression did not decrease stemness or global parameters of metabolism in colorectal cancer cell lines." (PMID 41801951, 2026).
psoriasis (1 paper, 2022). An autoimmune condition characterized by red, well-delineated plaques with silvery scales that are usually on the extensor surfaces and scalp. "Of interest, we identified 3 overlapping DEGs (HEATR6, HLA-DRB5, and MRPL54) between psoriasis neutrophils with and without stimulation of keratinocytes in relative to healthy neutrophils." (PMID 35401573, 2022).
tumor (1 paper, 2020). "Four genes (MRPL54, ZC3H13, IFIT5, and PPARGC1A) were downregulated and may function as tumor suppressor genes in HCC, and showed a positive correlation with prognosis." (PMID 33251144, 2020).
MRPL54 also shares sentences with these, for which no sentence is quoted: cancer (2 papers); asthma (1); colon cancer (1); leukemia (1); liver cancer (1); lung adenocarcinoma (1).